FOXP3 (forkhead box P3)
Diseases named in the same sentence as FOXP3 in open-access papers (continued):
Sharing a sentence is not in itself a finding about the gene and the disease.
myeloma (15 papers, 2010 to 2024). "Similarly, decreased LAG3 expression on CD4+Foxp3+ T cells was associated with significantly longer PFS in patients with multiple myeloma." (PMID 39456740, 2024). "Using animal models of multiple myeloma, we found that both the depletion of all FoxP3+ Tregs and the selective ablation of IFNAR1 on Tregs induced tumor remission in an aggressive murine myeloma model." (PMID 38993887, 2023). "Previously, our group studied the role of type I IFNs in animal models of multiple myeloma, finding that myeloma cells in the tumor microenvironment recruit FoxP3+ regulatory T cells (Tregs) through IFNAR signaling to escape immune surveillance." (PMID 38993887, 2023). "We investigated dynamics of CD4+FOXP3+ T cell recovery following the high-dose chemotherapy (HDC) with autologous hematopoietic stem cell transplantation (auto-HSCT) in multiple myeloma (MM) patients." (PMID 29930767, 2018). "Further, we tried to assess a possible direct impact of BM myeloma plasma cells (PCs) on the counts of peripheral blood (PB) CD4+FOXP3+ T cells." (PMID 29930767, 2018). "For examples, infusion of myeloid DCs and systemic administration of IL-2 have been shown to induce and expand CD4+FoxP3+ Tregs in myeloma and renal cancer patients." (PMID 21106069, 2010). "In addition, in another study, the reconstituted bone marrow-residing CD4+CD25+FOXP3+ Treg of the myeloma patients after allogeneic stem cell transplantation consisted preferably of CD45RA−CCR7- memory T cells." (PMID 39335199, 2024). "Notably, depleting FoxP3+ Tregs in myeloma-inoculated mice reinstated immunological recognition of the oncogenic cells and facilitated tumor remission—with Treg-specific ablation of IFNAR recapitulating this very effect." (PMID 38993887, 2023). "Furthermore, co-culture of primary myeloma cells with CD4+/CD25−/FOXP3− T cells induced increased amount of inducible Tregs (CD4+/CD25+/FOXP3+)." (PMID 28482851, 2017). "Indirectly, the relationship of Treg functional activity and FOXP3 isoforms expression is confirmed by data on the level of FOXP3 isoforms expression in Treg during their differentiation in the human thymus, as well as in multiple myeloma and chronic inflammatory bowel diseases." (PMID 30405716, 2018). "Furthermore, DCs loaded with chaetocin-treated dying myeloma cells most potently inhibited CD25+Foxp3+ T cells, increased the proportion of CD8+ T cells, induced Th1 polarization and generated the most potent myeloma-specific CTLs compared with DCs loaded with UVB-irradiated dying myeloma cells." (PMID 28512265, 2017). "In this study, we observed the overexpression of FOXP3 and CTLA4 in the BM of myeloma patients when compared to healthy controls." (PMID 25099367, 2014). "As evaluated through the combined staining with CFSE and anti-FoxP3 mAb, IDO+ myeloma cells induced an expansion of the overall Treg population." (PMID 23232072, 2012). "Therefore, our finding of an increased expression of FOXP3 and CTLA4 in BM of MM patients suggests an accumulation of immunosuppressive Tregs in the tumor microenvironment of myeloma patients." (PMID 25099367, 2014). "Also, relative and absolute counts of PB CD4+FOXP3+ T cells did not correlate with the relative count of BM myeloma PCs: rS=0.17, p=0.35, and rS=0.11, p=0.55, respectively." (PMID 29930767, 2018).
pancreatic ductal adenocarcinoma (15 papers, 2015 to 2024). An infiltrating adenocarcinoma that arises from the epithelial cells of the pancreas. "CCL5, activated by cancer FOXP3, is responsible for FOXP3 + Treg cells infiltration in pancreatic ductal adenocarcinoma." (PMID 36569832, 2022). "Forkheadbox protein 3 (FOXP3), a pivotal transcription factor for regulation of T cells, has been identified as a key regulator in pancreatic ductal adenocarcinoma." (PMID 34541823, 2021). "FOXP3+RORγt+ Tregs were increased in PBMC from patients with pancreatic ductal adenocarcinoma, and they produced IL-17A and expressed high level of LAG3." (PMID 31354747, 2019). "Cancer-FOXP3 directly activates CCL5 to recruit FOXP3+ Treg cells in pancreatic ductal adenocarcinoma." (PMID 31221150, 2019). "Another research indicates that immunotherapy combined with blockade of PD-L1 and CCL-5 may provide an effective treatment for patients with pancreatic ductal adenocarcinomas (PDAC) with high cancer Forkhead box protein 3 (Cancer-FOXP3 or C-FOXP3) levels." (PMID 36387070, 2022). "We examined the prognostic value of programmed cell death-1 (PD-1) and its ligand (PD-L1) together with CD8+ tumor-infiltrating lymphocytes (TILs) and FOXP3+ Tregs in resectable pancreatic ductal adenocarcinoma (PDAC) samples treated with adjuvant chemotherapy." (PMID 27329602, 2016). "Moreover, a role of FOXP3 in pancreatic ductal adenocarcinoma has been reported." (PMID 34541823, 2021). "In pancreatic ductal adenocarcinoma, CXCL10 has been shown to recruit CD4+, CD8+, and CXCR3+ T cells as well as FOXP3+ Tregs27." (PMID 34504204, 2021). "Recent research has shown that FoxP3+ Treg accumulation within the TME can indicate a worse prognosis of cancer patients, including those suffering from ovarian and pancreatic ductal adenocarcinomas." (PMID 31906017, 2019). "Immunohistochemistry was used to explore the clinical significance of CD3, CD4, CD8, FoxP3, and PD-L1 expression within the TME and to identify correlations with the prognosis of PC in a series of 29 patients with ASCP and 54 patients with pancreatic ductal adenocarcinoma (PDAC)." (PMID 36835933, 2023).
abortion (14 papers, 2010 to 2023). the ending of pregnancy by removing a fetus or embryo before it can survive outside the uterus. "In patients with recurrent spontaneous abortion, the expression of Foxp3 protein in peripheral blood and decidual tissues is significantly less than that in normal pregnant women." (PMID 34458378, 2021). "Similarly, in another murine study mitigation of FOXP3+ Treg induction during pregnancy was used and resulted in antigen-specific fetal loss and adoptive transfer of Treg from normal pregnant mice to abortion prone mice prevented fetal resorption in the abortion prone mouse model." (PMID 31921098, 2019). "Collectively, the findings suggested that ESA restricted Foxp3 expression by inhibiting TGFßRII/Smad2/Smad3/Smad4 signalling, ultimately resulting in abortion." (PMID 28300338, 2017). "The data show that ESA or RU486 did indeed attenuate the frequency of CD4+CD25+Foxp3+ T cells in abortion‐prone mice." (PMID 28300338, 2017). "On day 12 of pregnancy, we found an augmented number of CD4+ Foxp3+ Treg cells in the decidua of abortion-prone females that received hCG-treated BMDCs when compared to females that received mature BMDCs." (PMID 27895621, 2016). "In our study, we have also found that ESA could negatively moderate Foxp3 in pregnant mice, and hence, speculate that ESA inhibits the function of Tregs via suppression of Foxp3, ultimately resulting in abortion." (PMID 28300338, 2017). "Consequently, Foxp3+CD4+CD25+ cells from CD4+CD25−Foxp3− cells by FTY720-induced conversion were adoptively transferred into abortion-prone NOD mice." (PMID 24714634, 2014). "DT administration did not induce CD45+Foxp3+ cell populations in bvPLA2-treated abortion-prone mice (the d-LPS + bvPLA2 group)." (PMID 31336883, 2019).
acute GVHD (14 papers, 2013 to 2024). "A (GT)n polymorphism in the promoter/enhancer region of forkhead box protein P3 (FOXP3) is associated with the development of severe acute graft-versus-host disease (GVHD) in humans." (PMID 39167800, 2024). "Further studies have shown Treg cells from patients with acute GVHD exhibited multiple dysfunctions, including Foxp3 expression instability and increased apoptosis." (PMID 37626859, 2023). "Previous studies in allo-HSCT animal models showed that the addition of highly purified CD4+CD25+FoxP3+Treg cells resulted in a reduction of acute GVHD." (PMID 38124750, 2023). "Our group has reported that the blockade of BAFF through belimumab therapy or blocking of IL-21 signaling plays critical roles in the generation of CD4+CD25+Foxp3+ Treg cells in acute GVHD after allo-BMT." (PMID 36561743, 2022). "Previous studies have reported that CD8+Foxp3+ regulatory T cells expanded after experimental allogeneic bone marrow transplantation in mice and mitigated experimental acute GVHD." (PMID 27377819, 2016). "Accumulating evidence suggests that a reduction in the number of Foxp3+ regulatory T cells (Tregs) contributes to the pathogenesis of acute graft-versus-host disease (aGVHD), which is a major adverse complication that can occur after allogeneic hematopoietic stem cell transplantation (allo-HSCT)." (PMID 31664223, 2020). "Interestingly, it has been demonstrated that G-MSCs not only express CD39 but also increase the frequency of CD39+Foxp3+ Tregs, which supports the generation of adenosine and promotes immune suppression of effector T-cells in vitro and in an acute GVHD model." (PMID 31766697, 2019). "In contrast, CD4+Foxp3+ splenocytes were increased in the curcumin-treated acute GVHD animals." (PMID 23840617, 2013). "We extended these studies on the potential induction of Foxp3 expression in CD4+ non-Treg by examining a cohort of patients who were developing acute GVHD or who manifested signs of chronic GVHD following HCT for malignancies." (PMID 37350974, 2023). "IL‐33 mediates the expansion of ST2+FOXP3+ Tregs via activation of p38 MAPK signaling after HSCT, which could protect against acute GVHD." (PMID 35474948, 2022).
adenoma (14 papers, 2014 to 2025). A neoplasm arising from the epithelium. "The density of ST2-positive cells in the adenoma/CRC stroma parallels the increased density of FoxP3-positive Tregs in the adenoma/CRC microenvironment, and is associated with the some advanced clinicopathological variables in both the adenoma/CRC and prognosis in patients with CRC." (PMID 32246094, 2020). "One study showed evidence of decreasing numbers of FOXP3+ Tregs throughout the sporadic adenoma–carcinoma sequence." (PMID 40149674, 2025). "Regarding IL-10 levels in premalignant and malignant CR lesions, double immunohistochemistry revealed more abundant CD4/CD25 and IL-10/FoxP3 dual-positive Tregs within the tumor stroma in both adenomas and carcinomas." (PMID 40149674, 2025). "This is illustrated by a meaningful rise in FOXP3+ Tregs in colorectal adenoma tissue compared to normal mucosa but only slightly elevated numbers of FOXP3+ Tregs in CRC compared to adenomas." (PMID 40149674, 2025). "This indicates that the occurrence of high FOXP3+ expression is an early event in the adenoma–carcinoma sequence." (PMID 40149674, 2025). "The mean number of Foxp3 was higher in carcinomas than in adenomas in all compartments (p < 0.000 for the intratumoral compartment and p = 0.018 for the adjacent stroma)." (PMID 36766393, 2023). "Our results showed that infiltration of Foxp3+ cells was low in normal mammary tissue, as already highlighted by previous authors, whereas only a small percentage of adenoma (35%) contained Treg lymphocytes." (PMID 36766393, 2023). "Regarding the comparison of the immune microenvironment between sporadic and hereditary FAP-related lesions, we observed a significantly lower density of Foxp3+ regulatory T cells in FAP adenomas with LGD, as compared with sporadic adenomas with LGD." (PMID 34575971, 2021). "The density of FoxP3-positive Tregs was even higher in the CRC stroma than that in the adenoma stroma (P < 0.01)." (PMID 32246094, 2020). "ST2 is highly expressed in tumors of CRC patients, which correlates with an increased expression of Foxp3 in both adenoma and CRC tissues." (PMID 32674255, 2020). "Increased abundance of FoxP3-positive Tregs was also demonstrated in both the adenoma/CRC epithelium and stroma, compared with the controls." (PMID 32246094, 2020). "Increased densities of FoxP3-positive Tregs were also observed in both the adenoma/CRC epithelium and stroma compared with the controls." (PMID 32246094, 2020). "Real-time PCR results revealed increased expression levels of ST2 and FoxP3 mRNAs in both adenoma and CRC tissues as compared with control tissues." (PMID 32246094, 2020). "Our quantitative PCR data also showed that bot the expression of ST2 and FoxP3 mRNAs were increased in adenomas and CRCs respectively compared to the controls." (PMID 32246094, 2020). "During the CRC development in the APCmin/+ mouse model, CD4+Foxp3+ Treg cells accumulate in the adenomas, which match with lower frequencies of conventional T and B cells in situ, indicating a downmodulation of the local immune response against CRC." (PMID 32674255, 2020). "Results showed that the expression of both ST2 and FoxP3 at the mRNA and cellular levels were significantly increased in the adenoma/CRC microenvironment." (PMID 32246094, 2020). "The image showed that FoxP3-positive cells in the adenoma/CRC epithelium were positive for CD3 and confirmed that the cells were lymphocytes, but not adenoma/CRC epithelial cells." (PMID 32246094, 2020). "IHC analysis confirmed increased densities of ST2-positive cells in both the adenoma/CRC epithelium and stroma, which show a close positive linear association with the densities of FoxP3-positive Tregs in respective compartments." (PMID 32246094, 2020). "The clinicopathological and prognostic significance of cellular ST2-positive cells and FoxP3-positive Tregs in patients with adenoma and CRC were evaluated." (PMID 32246094, 2020).
adenoma (continued). "Advantages and disadvantages of these two techniques have been discussed for years:67–69 we previously used quantitative real-time PCR as a high sensitive technique to quantify ST2 or FoxP3 at the mRNA level on only a tiny fraction of adenoma/CRC specimens." (PMID 32246094, 2020). "We saw increased expression of FOXP3+ T-reg cells in AIPpos tumors compared to sporadic adenomas and normal pituitary." (PMID 30867568, 2019). "Adenomas from Mutyh−/− mice had a greater infiltrate of Foxp3+ T regulatory cells, granulocytes, macrophages, MDSCs and strong expression of TGF-β-latency-associated peptide and IL6." (PMID 26109431, 2015). "Of note, we detected similar numbers of CD3+ cells and FoxP3+ cells in the adenomas in both groups suggesting that most of the T cells in the adenomas were Tregs." (PMID 24866282, 2014). "Also, ST11 K. pneumoniae increased the densities of the tumor-infiltrating FoxP3+ cells, which distributed primarily in the stromal region of adenomas." (PMID 34606408, 2021). "IHC were used to examine cellular expression of ST2 and FoxP3 in the adenoma/CRC microenvironment." (PMID 32246094, 2020). "YYFZBJS decreased expression levels of Foxp3, IL-6 and IL-10 in conventional T cells in adenomas." (PMID 32677955, 2020). "However, ST2 expression at cellular level in the adenoma stroma was correlated with the density score of FoxP3-positive Tregs in the same compartment." (PMID 32246094, 2020). "Similarly, the mRNA expression of FoxP3 were increased to a ~4.8-fold higher level in the adenoma tissues and to a 5.6-fold higher level in the CRC tissues (both P < 0.05)." (PMID 32246094, 2020). "In addition, correlational analysis showed that cellular expression of ST2-positive stromal cells in the adenoma was correlated with the expression of FoxP3-positive Tregs in the adenoma stroma." (PMID 32246094, 2020). "Compared to those in wild-type mice, adenomas from Mutyh−/− mice showed a distinct infiltrate of Foxp3+ regulatory T cells, along with a concomitant strong expression of TGF-β1 latency-associated peptide (LAP) visible both in infiltrating cells and in the dysplastic epithelium." (PMID 26109431, 2015). "Thus, whereas adenomas from wild-type and KO mice are similarly infiltrated by CD3+ T lymphocytes, Mutyh−/− adenomas contain significantly more regulatory T cells (Tregs, Foxp3+)." (PMID 26109431, 2015). "Interestingly, in our study it appears that the vast majority of the CD3+ T cells in adenomas of APCMIN/+ mice are Tregs as determined by expression of FoxP3." (PMID 24866282, 2014). "Furthermore, single-cell RNA-sequencing data showed that the expression of IL-2RA (CD25) and FOXP3, the key markers of Treg cells, was increased from adenoma to carcinoma in the tissue-derived CD4+ T cells, which is consistent with the changes in peripheral Treg cells." (PMID 38343544, 2024). "We found that adenomas with LGD from FAP patients displayed a marginal increase in CD8+ T cells (p < 0.05) and a significantly lower density of Foxp3+ (p < 0.0001) T cells when compared with sporadic adenomas with LGD." (PMID 34575971, 2021). "In the stroma of our adenomas, macrophages (CD68+) were slightly more numerous than CD8+ or FOXP3+ T cells, but they were far less abundant than CD4+ T cells." (PMID 27441558, 2016). "In all three categories—normal tissue, adenoma, and CRC—FOXP3+ Tregs rarely infiltrate the epithelium, with FOXP3+cell infiltration predominantly observed in the lamina propria in healthy tissue, in the adenomatous stroma in premalignant lesions, and in the tumor stroma in CRC." (PMID 40149674, 2025). "The density of FoxP3-positive Tregs in both adenoma epithelium and stroma correlated neither with histological types nor dysplastic degree grading." (PMID 32246094, 2020).
adenoma (continued). "Therefore, we analyzed correlations between the densities of ST2-positive cells and FoxP3-positive Tregs in different compartments of the adenoma/CRC microenvironment and the clinicopathological variables in patients with adenoma/CRC." (PMID 32246094, 2020). "AIPpos tumors also expressed a significantly higher number of FOXP3+ T-reg cells compared to sporadic adenomas (P = 0.02) or normal tissues (P = 0.01)." (PMID 30867568, 2019). "There was minimal infiltration of CD3+ cells, FoxP3+ cells, or B220+ cells in adenomas in either group when compared to adjacent non-tumor epithelium." (PMID 24866282, 2014). "However, FOXP3+ Tregs do not always show a substantial and stepwise increase in normal mucosa–adenoma–carcinoma tissues." (PMID 40149674, 2025). "In biopsies of the distal colon without adenomas and carcinomas, there was a lower level of gene expression of Rorγt and higher gene expression of Foxp3 in IL-10KO/IL-37tg mice indicating a tumor protective immune status associated with transgene IL-37 expression." (PMID 31781119, 2019). "The analysis showed that the expression level of ST2 mRNA in both adenoma and CRC tissues were not correlated with the expression level of FoxP3 mRNA." (PMID 32246094, 2020).